MSR1 (macrophage scavenger receptor 1)
Diseases named in the same sentence as MSR1 in open-access papers (continued):
Sharing a sentence is not in itself a finding about the gene and the disease.
prostate carcinoma (continued). "Although rare variants of other genes such as RNASEL, MSR1, and ELAC2 have been previously identified in prostate cancer families and proposed as prostate cancer susceptibility alleles, follow-up studies have not supported their candidacy." (PMID 23064873, 2013). "The expression of the macrophage scavenger receptor 1 (MSR1) was suggested to label a subset of anti-tumor TAMs, being significantly correlated with the inhibition of tumor progression, lower clinical stage, recurrence-free survival, and good prognosis in prostate cancer patients." (PMID 32456204, 2020). "For prostate cancer, we analyzed 5 genes and did not observe an over-representation of SNP associations at p<0.05 (observed/tested: BRCA2, 2/83; ELAC2, 1/9, HOXB13, 0/2; MSR1, 1/22; RNASEL, 2/21)." (PMID 23555315, 2013).
breast carcinoma (22 papers, 2007 to 2026). "Beyond TNBC, we also explored the expression of CPVL and MSR1 in macrophages in other molecular subtypes of breast cancer using bulk RNA sequencing." (PMID 39776914, 2024). "Furthermore, single-cell profiling of myeloid cells from patients with breast cancer identified lipid-associated macrophages that co-expressed the TTR macrophage markers CD63, LIPA, GPNMB, MCR1, CD163, and MSR1." (PMID 38942020, 2024). "To investigate whether CPVL and MSR1 have prognostic significance in other intrinsic molecular subtypes of breast cancer, we analyzed their gene expression from 643 patients from the TCGA database." (PMID 39776914, 2024).
lung carcinoma (17 papers, 2012 to 2025). "For example, reduced expression levels of MSR1 in tumors, such as lung cancer and melanoma, may be associated with invasion, metastasis, and poor prognosis." (PMID 37671167, 2023). "In our study, however, no increased expression of Msr-1 as a protein on the surface of peripheral blood DCs was observed in lung cancer patients (data not shown)." (PMID 29850632, 2018).
melanoma (12 papers, 2015 to 2025). A malignant, usually aggressive tumor composed of atypical, neoplastic melanocytes. "It was further demonstrated that MSR1 inhibition or deletion improved the ability of DCs to generate antitumour responses to melanoma, improving the expansion and activation of CD8+ T cells specific for melanoma antigens." (PMID 36325338, 2022). "Isoforms of MSR1 were differentially expressed in primary melanomas and benign melanocytic nevi." (PMID 36325338, 2022). "Among the top genes with differentially spliced isoforms between primary melanomas and benign melanocytic nevi were RAB6B, MSR1, LYPD1, and COL11A2." (PMID 34281234, 2021).
pancreatic cancer (12 papers, 2015 to 2025). "Evidence has been provided showing that sequence variants of the MSR1 gene are associated with short overall survival in pancreatic cancer patients." (PMID 34281234, 2021). "Sequence variants of the MSR1 gene are associated with pancreatic cancer, namely, among families affected with hereditary pancreatic cancer, where six rare missense mutations and one nonsense germline mutation were found in MSR1." (PMID 34281234, 2021). "High co-expression of CD44/CD133 and CD204 (MSR1) was associated with short overall survival in another study on pancreatic carcinoma." (PMID 34281234, 2021). "In MSR1‐deficient mice, ovarian and pancreatic cancer development was significantly inhibited." (PMID 35142109, 2022). "Fucoidan, poly I, and poly G were able to inhibit tumour progression and invasion via MSR1 in ovarian and pancreatic cancer models." (PMID 36325338, 2022). "In pancreatic cancer, MSR1+ macrophages were found within the TME and at the migratory front of the cancer which was associated with tumour aggressiveness." (PMID 36325338, 2022). "However, a small 16-amino acid amphipathic peptide, 4F, inhibited MSR1 and drastically reduced the invasion of ovarian and pancreatic cancer cells, and reduced tumour growth in vivo." (PMID 36325338, 2022). "Interestingly, MSR1 has been previously shown to promote tumour progression and metastasis in ovarian and pancreatic cancer mouse models, suggesting that MSR1 and downstream signalling may be a potential drug target in the prevention of cancer metastasis progression." (PMID 31028084, 2019). "Recent studies have shown significant inhibition of ovarian and pancreatic cancer development in mice lacking MSR1." (PMID 39502334, 2024).
Obesity (11 papers, 2014 to 2024). Accumulation of substantial excess body fat. "Through differential gene expression analysis, WGCNA, and machine learning methods, we identified three biomarkers (IL6R, GZMB, and MSR1) associated with obesity." (PMID 39502334, 2024). "In this study, we found that MSR1 is upregulated in obesity, associated with inflammation-related immune cells such as macrophages and natural killer cells, while in THCA, it enhances the activity of macrophages, dendritic cells, and T cell subsets." (PMID 39502334, 2024). "However, it is important to note that this study has certain limitations and shortcomings, primarily stemming from the lack of a more profound investigation into the mechanisms underlying MSR1’s role in the interplay between obesity and THCA." (PMID 39502334, 2024). "In this study, we integrated various advanced techniques, including WGCNA, PPI network analysis, and machine learning algorithms, to identify the key gene MSR1 and assess its diagnostic value for obesity and THCA patients, ensuring the depth and breadth of the research findings." (PMID 39502334, 2024). "Together, these results suggest that MSR1 may play a role in obesity-associated insulin resistance and adipose tissue inflammation, but the precise mechanisms are unclear." (PMID 36788340, 2023). "We were unable to replicate prior studies suggesting that Msr1-deficient mice were more susceptible to inflammation with HFD induced obesity and instead initially observed that Msr1-deficient mice were protected from HFD-induced obesity and adipose tissue inflammation." (PMID 36788340, 2023). "Macrophage scavenger receptor 1 (MSR1) has been implicated in the regulation of adipose tissue inflammation and diabetes pathogenesis; however, reports have been mixed on the contribution of MSR1 in obesity and glucose intolerance." (PMID 36788340, 2023). "Thus, we hypothesize that MSR1 is a crucial factor underlying the link between obesity and THCA, providing novel targets for future therapeutic strategies for these two diseases." (PMID 39502334, 2024). "The established ROC curve results also indicate high diagnostic value of GZMB (AUC: 0.857), MSR1 (AUC: 0.959), and IL6R (AUC: 0.857) for obesity." (PMID 39502334, 2024). "This study, through the integration of bioinformatics analysis and machine learning, has discovered that MSR1 can influence the occurrence and development of obesity and THCA by modulating the infiltration of immune cells." (PMID 39502334, 2024). "Subsequent immune infiltration analysis revealed that MSR1 can modulate specific types of immune cells to influence the immune microenvironment in obesity and THCA, thereby impacting the development of both diseases." (PMID 39502334, 2024). "The ROC curve results also demonstrate high diagnostic value of GZMB (AUC: 0.790), MSR1 (AUC: 0.959), and IL6R (AUC: 0.857) for obesity." (PMID 39502334, 2024). "This study aimed to elucidate the role of Msr1 in insulin resistance and adipose tissue inflammation during obesity." (PMID 36788340, 2023). "Researchers used monoclonal antibodies to target MSR1 in obesity-related NAFLD mouse models and found that foam macrophages and inflammatory factors were significantly reduced." (PMID 37020267, 2023). "As MSR1 levels are increased in visceral adipose tissue in obesity, further in vitro experiments of visceral adipocytes demonstrated that MSR1-mediated increase of ox-LDL uptake stimulates the pro-inflammatory responses." (PMID 36591228, 2022). "We used mice that had a genetic deletion of Msr1 or Marco to determine if different Class A Scavenger receptors were relevant to obesity‐induced insulin resistance." (PMID 30485705, 2018). "The heatmap reveals that GZMB upregulates the expression levels of monocytes, dendritic cells, and eosinophils in obesity, MSR1 upregulates the expression levels of macrophages and natural killer cells in obesity, and IL6R upregulates the expression levels of dendritic cells in obesity." (PMID 39502334, 2024).
Obesity (continued). "For instance, pharmacological agents that enhance or inhibit MSR1 activity could be explored as potential treatments for obesity-related THCA." (PMID 39502334, 2024). "Overall, these findings suggest that MSR1 may serve as a significant biomarker linking obesity and thyroid cancer." (PMID 39502334, 2024). "Our research indicates that MSR1 may influence the occurrence and development of obesity and THCA by regulating the infiltration level of immune cells." (PMID 39502334, 2024). "This confirms MSR1 as an important biomarker regulating both obesity and THCA." (PMID 39502334, 2024). "Overall, we conclude that while MSR1 is a biomarker of diabetes status in human adipose tissue, in mice Msr1 is not required for obesity-associated insulin resistance or ATM accumulation." (PMID 36788340, 2023). "Despite the clinical association between MSR1 expression and T2D, there is evidence from mouse studies suggesting that Msr1 may regulate beneficial macrophage functions to protect against obesity-induced insulin resistance." (PMID 36788340, 2023). "We examined if Msr1 was required for obesity-induced ATM infiltration and proliferation." (PMID 36788340, 2023). "To address these gaps and evaluate the hypothesis that MSR1 promotes ATM proliferation, we set out to examine the role for Msr1 in diet induced obesity in mice and humans." (PMID 36788340, 2023). "Overall, these observations indicate that Msr1 is not required for obesity-associated adipose tissue inflammation and ATM infiltration and demonstrates that ATM proliferation is more robust in females compared to males." (PMID 36788340, 2023). "Our findings suggest that Msr1 does not play a significant role in controlling obesity-associated insulin resistance and inflammation." (PMID 36788340, 2023). "Furthermore, mRNA levels of MSR1, CD36, and LOX-1 in whole adipose tissue specimens have been associated with obesity and insulin resistance in humans." (PMID 25224267, 2014). "Therefore, MSR1’s role as a therapeutic target not only has implications for understanding disease mechanisms but also provides a pathway for clinical applications aimed at obesity and THCA treatment." (PMID 39502334, 2024). "Therefore, to enhance the translational potential of this research, it will be essential to strengthen our understanding of the functional role of MSR1 through experimental validation and to explore its potential applications in the treatment of obesity and THCA." (PMID 39502334, 2024). "In the validation group, GZMB, MSR1, and IL6R were similarly significantly upregulated in adipose tissues of the obesity group." (PMID 39502334, 2024). "Initially, in the training dataset GSE44000, we observed significant upregulation of GZMB, MSR1, and IL6R in adipose tissues of the obesity group." (PMID 39502334, 2024). "Overall, our experiments do not support a functional role for MSR1 in obesity-induced adipose tissue inflammation despite being a biomarker for ATM content." (PMID 36788340, 2023). "Because Msr1KO mice had significantly less Msr1 expression in their adipose tissue compared to their Msr1HET littermates, we still feel this rigorously tests the requirement for Msr1 in HFD induced obesity." (PMID 36788340, 2023). "Initial studies suggested protection from diet induced obesity in Msr1−/− mice compared to non-littermate controls." (PMID 36788340, 2023). "Compared to wild‐type (WT) mice, Msr1−/− mice had worse blood glucose control that was only revealed after diet‐induced obesity, not in lean mice." (PMID 30485705, 2018). "The final analysis revealed that MSR1 is closely related to the degree of immune cell infiltration in patients with obesity and THCA, suggesting that this gene may be a potential intervention target for both obesity and THCA." (PMID 39502334, 2024).
Obesity (continued). "Among them, the upregulated gene BCL2A1 is common in CVD, HTN, obesity, and aging; RNF144B and PTGIS are common in HCL, obesity, aging, and CVD; G0S2, CXCL1, ACKR3, and PTPRD are found in HTN, aging, and CVD; TGFB2, CA12, and MSR1 are familiar in obesity, aging, and CVD." (PMID 36035865, 2022).
Alzheimer disease (8 papers, 2021 to 2025). A progressive, neurodegenerative disease characterized by loss of function and death of nerve cells in several areas of the brain leading to loss of cognitive function such as memory and language. "One potential method of enhancing MSR1 activity to aid the clearance of β-amyloid was highlighted during the development of a novel early diagnostic tool for Alzheimer’s disease." (PMID 36325338, 2022). "Adding further to the positive effects of MSR1 expression in Alzheimer’s disease, MSR1 expression is reduced in the ageing brain concomitantly with increased β-amyloid deposition and reduced working memory capacity." (PMID 36325338, 2022). "Through downstream analysis, we highlight disease-relevant, translatable pQTLs by presenting new evidence supporting protein-disease associations; most notably, CD33 and Alzheimer’s disease, GPNMB and Parkinson’s disease, and MSR1 and schizophrenia." (PMID 34857772, 2021). "Using two-sample Mendelian randomisation, we identify causal associations between serum CD33 and Alzheimer’s disease, GPNMB and Parkinson’s disease, and MSR1 and schizophrenia, describing their clinical potential and highlighting drug repurposing opportunities." (PMID 34857772, 2021). "The role of Msr1 in neurodegeneration such as Alzheimer’s disease (AD) was first highlighted in an in vitro study showing that it could facilitate adhesion of microglia to fibrillar Aβ." (PMID 33758958, 2021). "Of these proteins, MSR1 and CTSS are also upregulated in a blood transcriptomic study of individuals with comorbid PTSD and Alzheimer’s disease." (PMID 35625844, 2022).
ovarian carcinoma (8 papers, 2013 to 2024). A malignant neoplasm originating from the surface ovarian epithelium. "IL10, IL6, IL6ST, and macrophage scavenger receptor 1 (MSR1; CD204) were positively correlated with ovarian cancer patients in the high-risk group using heatmap analyses of the signature with the immune-related genes." (PMID 33381581, 2020). "While previously it was shown that lack of MSR1 delayed the growth of EL4 lymphoma in mice by increased pro‐inflammatory responses to necrotic cells, our data revealed an increased expression of K63‐polyubiquitylated MSR1 in a human ovarian cancer." (PMID 31028084, 2019). "MSR1 was also found to be expressed in the VLCs in ovarian cancer." (PMID 36325338, 2022). "Interestingly, the TAMs of the patient with ovarian cancer also showed increased levels of ubiquitylated MSR1 as well as enhanced phosphorylation of JNK and its substrate c‐Jun." (PMID 31028084, 2019). "Besides the use of IHC to analyse MSR1+ TAMs, flow cytometry also provides a multiparameter analysis to study cell invasion and tumour metastasis of breast cancer, gastric cancer, oral squamous cell carcinoma, and ovarian cancer." (PMID 36325338, 2022). "Moreover, MSR1 K63 polyubiquitylation correlated with the activation of JNK signalling in ovarian cancer tissue from human patients, suggesting that it may be relevant for macrophage phenotypic shift in vivo." (PMID 31028084, 2019). "We demonstrate that MSR1 is K63‐ubiquitylated and signals through JNK in human patient ovarian cancer, thus suggesting a potential role in human cancer." (PMID 31028084, 2019).
asthma (7 papers, 2015 to 2024). "MSR1 was associated with asthma and was postulated by our group as a very good biomarker candidate for severity in several respiratory diseases." (PMID 29977241, 2018). "The expression of MSR1 has been described in fibrocytes, controversial cells located in peripheral blood samples; the definition of these cells has been challenging to characterize, and it has recently been associated with uncontrolled asthma, asthma exacerbations, and chronic obstructive asthma." (PMID 35268530, 2022). "MSR1 expression is significantly increased in peripheral blood mononuclear cells (PBMCs) from patients with asthma and COPD." (PMID 39684750, 2024). "The aim of this study was to validate previous results from our group relating MSR1 with asthma and, due to its description mainly as a receptor expressed on macrophages or tissue cells, to characterize their cellular origin in peripheral samples." (PMID 35268530, 2022). "Overall, these results provide new evidence of the potential role of MSR1 in patients with asthma and COPD." (PMID 35268530, 2022). "MSR1 gene and protein expression differed according to asthma and COPD clinical phenotype, reinforcing the possible role of MSR1 in these diseases." (PMID 35268530, 2022). "Again, the two groups with asthma showed higher MSR1 gene expression than healthy controls in all the clinical phenotypes, although this seemed to be higher in the group with moderate–mild AA diagnosis." (PMID 35268530, 2022). "MSR1 is mainly expressed on macrophages and dendritic cells, and recent studies have found that MSR1 is also present on the surface of lymphocytes and may be involved in the pathogenesis of asthma and chronic obstructive pulmonary disease." (PMID 36591228, 2022). "MSR1 was one of the most overexpressed genes in the PBMCs of a population of AA subjects, despite the fact that it had never been associated with asthma." (PMID 35268530, 2022). "This study tries to define subpopulations of PBMCs that could be responsible for the MSR1 gene expression differences detected in asthma and COPD." (PMID 35268530, 2022). "Previously reported overexpressed (IL-10, MSR1, PHLDA1, SERPINB2, and CD86) and underexpressed genes (CHI3L1, CPA3, IL-8, and PI3) in severe asthma were analyzed by RT-qPCR in peripheral blood mononuclear cells (PBMCs)." (PMID 37445432, 2023). "According to the severity of asthma and COPD, the severe NA group (44.98 ± 7.14%) had higher amounts of MSR1+ cells than the C (34.36 ± 9.30%, p = 0.0408) and moderate–mild NA groups (32.27 ± 6.42%, p= 0.0125)." (PMID 35268530, 2022). "MSR1 was the most overexpressed gene in severe nonallergic asthma (NA) compared to healthy controls; its presence at the protein level was confirmed, and interesting differences between NA and allergic asthmatic (AA) subjects were discovered." (PMID 35268530, 2022). "In a recent work, new gene and protein biomarkers CHI3L1, IL-8, IL-10, MSR1, PHLDA1, PI3, and SERPINB2, were proposed to discriminate healthy control subjects from nonallergic asthmatic patients (T2-low) and to measure asthma severity." (PMID 31143187, 2019).
gastric cancer (7 papers, 2015 to 2025). A primary or metastatic malignant neoplasm involving the stomach. "Previous studies have shown that silencing MSR1 reduces macrophage polarization towards M2 in TME of gastric cancer, which agrees with our results." (PMID 39776914, 2024).
glioblastoma (7 papers, 2019 to 2024). The most malignant astrocytic tumor (WHO grade IV). "In addition to changes in Mmps, we also found that glioblastoma was associated with an increased expression of mRNAs encoding microglial phagocytic receptors—Cd93, Msr1, Cd36, Olr1, Megf10, Clec7a, and Scarf1." (PMID 32299465, 2020).